CD47 (CD47 molecule)
Diseases named in the same sentence as CD47 in open-access papers (continued):
Sharing a sentence is not in itself a finding about the gene and the disease.
Burkitt lymphoma (7 papers, 2017 to 2026). A rare form of malignant mature B-cell non-Hodgkin lymphoma. "The SIRPα knockout M1 macrophages were then subjected to ADCP assays with CFSE-labeled Raji target cells, a cancer cell line derived from a Burkitt lymphoma and expressing CD47 and CD20 on their surface." (PMID 36077152, 2022). "It showed synergistic effect in renal carcinoma cell lines compared to anti-CD70 vorsetuzumab and anti-CD47 drugs alone or in combination, however its therapeutic effect did not outperform combination of the individual drugs when tested in a Burkitt lymphoma mouse model." (PMID 32677994, 2020). "We find that CD47 is expressed on the surface of three B-cell lines from human malignancies: 697 (pre-B-ALL lymphoblasts), Ramos and DG-75 (both mature B-cells, Burkitt’s lymphoma), and anti-CD47 antibodies greatly increase the phagocytosis of all three cell line by macrophages." (PMID 28977832, 2017). "Interestingly, the dissemination of tumor cells in a Burkitt lymphoma (BL) model was dependent on the level of CD47 expression." (PMID 32677994, 2020). "In this assay human peripheral blood-derived macrophages that endogenously express SIRPα are co-incubated with Burkitt’s lymphoma Raji cells (expressing both CD20 and CD47)." (PMID 31801627, 2019). "We found that CD47 was expressed on the surface of the three human B-cell lines used: 697 (pre-B-ALL), Ramos and DG-75 (both mature B-cells, Burkitt’s lymphoma))." (PMID 28977832, 2017).
head and neck cancer (7 papers, 2021 to 2025). A primary or metastatic malignant neoplasm affecting the head and neck. "In general, most cancer types with CD47 alteration/amplification, such as ovarian, esophageal, endometrial, and head and neck cancers, seemed to respond to CD47-SIRPα blockade." (PMID 36439116, 2022). "CD47 is also expressed in head and neck cancer and is a poor prognostic factor." (PMID 40940867, 2025). "Similarly, head and neck cancer patients with tumors bearing robust CD47 immunohistochemistry staining had diminished overall survival, compared with those with low CD47 staining." (PMID 34944850, 2021). "Therefore, approaches using anti-CD47 or anti-SIRPα antibodies to induce phagocytosis of cancer cells by TAMs have been attempted, and it has been reported that blocking human head and neck cancer cells with CD47 and anti-CD47 antibodies increases phagocytosis by macrophages." (PMID 40940867, 2025).
liver fibrosis (7 papers, 2017 to 2025). "Blockading the integrin-associated protein CD47/SIRP can reduce hepatic fibrosis." (PMID 40573105, 2025). "Blocking the CD47-SIRPα axis has been demonstrated to promote the phagocytic clearance of necHCs by liver macrophages, thus inhibiting the progression of liver fibrosis." (PMID 40630093, 2025). "Upregulated CD47, triggered by the YAP and TEAD4 genes, leads to the heightened activation of HSCs, resulting in liver fibrosis." (PMID 40786064, 2025). "For example, AAV-mediated silencing of CD47, KDM4D and nestin has been used as a strategy to reduce liver fibrosis." (PMID 38267432, 2024). "In addition, novel pathways pertaining to liver fibrosis, such as the RSPO3-LGR4/5-β-catenin cascade, the CD47/YAP/TEAD4 signalling axis, and HAb18G/CD147, are briefly elaborated in the context of therapeutic approaches for arresting HSC activation." (PMID 40786064, 2025). "Therefore, silencing or knocking down the CD47/YAP/TEAD4 pathway can inhibit the fibrotic gene expression, thereby attenuating liver fibrosis pathology." (PMID 40786064, 2025). "However, in CD47 knockout (CD47KO) mice, the phosphorylation and nuclear translocation of the p65 subunit of NF-κB were significantly enhanced, promoting the progression of MASLD and liver fibrosis." (PMID 40630093, 2025).
periodontitis (7 papers, 2020 to 2025). An acute or chronic inflammatory process that affects the tissues that surround and support the teeth. "Subsequent flow cytometry assay confirmed that loss of OTUD1 facilitated CD9 and CD47 surface expression in neutrophils during periodontitis and peritonitis." (PMID 37639212, 2023). "In the current study, we found a higher CD47 expression in M1 macrophages of periodontitis-affected tissues." (PMID 32210958, 2020). "We also found higher CD47 expression on monocytes isolated from periodontitis-affected gingival tissues versus healthy tissues." (PMID 32210958, 2020). "We found an increased expression of PDL1 and CD47 in periodontitis affected sites compared to healthy sites of patients with T2DM (p < 0.05)." (PMID 32210958, 2020). "Consistent with this notion, we found a significant over-expression of PDL1 and CD47 in M1 macrophages isolated from periodontitis-affected tissues compared to healthy tissues (p < 0.05)." (PMID 32210958, 2020). "On the DL-P vs. H comparison, which evaluated the effect of the dyslipidemia and periodontitis, the qPCR confirmed that the HLADRB4 and CD47 (CD47 molecule) genes were upregulated in H, while the DAB2 (DAB adaptor protein 2) gene was downregulated in H." (PMID 32424199, 2020). "In subjects with DL plus periodontitis versus HS, three DEG were confirmed (DAB2, CD47, and HLADRB4), and in the comparison between subjects with periodontitis alone versus HS: the IGHG3 gen (IGHDL-P) was upregulated, and the ITGB2 and HLADRB4 genes were downregulated." (PMID 36233348, 2022). "However, the protein expression of Ceacam1 in periodontitis, the role of Ceacam1 in alveolar bone remodeling, and the interaction between Ceacam1 and CD47 were not examined in the present study." (PMID 38549147, 2024).
prostate tumors (7 papers, 2015 to 2023). "Contrastingly, we observed that metastatic prostate tumors frequently expressed lower CD47 levels, compared with primary tumors and benign hyperplasia samples 19–21." (PMID 37848444, 2023). "Based on previous reports from our lab and others, Kaiso is associated with EMT reprogramming in high-grade breast and prostate tumors, Kaiso may also mediate immune modulation through the downregulation of THBS1 directly and upregulation of CD47 indirectly." (PMID 37190208, 2023).
squamous cell carcinoma (7 papers, 2019 to 2023). A carcinoma arising from squamous epithelial cells. "The results indicate that CD47 expression may prevent NK cell responses, consistent with an association between CD47 expression and protection from NK cell‐mediated cytotoxicity that was described previously in a study of squamous cell carcinoma lines." (PMID 32585084, 2020). "To disrupt the inhibitory axis, we generated a CD47 KO of the epidermoid carcinoma cell line, A431." (PMID 37444515, 2023). "The expression patterns of CD47 in basal cell carcinoma (BCC), squamous cell carcinoma (SCC) and its precursor lesions, and its clinicopathological significance were investigated." (PMID 36010209, 2022). "Out of 58 squamous cell carcinomas 21 (36.2%) were negative for CD47, 20 (34.5%) had medium expression and 17 (29.3%) had high expression." (PMID 35406573, 2022).
stomach cancer (7 papers, 2020 to 2024). "Herein, we isolated lung tissues from experimental gastric tumour models in Bev plus anti-CD47-treated cells to elucidate tumour metastasis." (PMID 35694254, 2022). "Furthermore, to detect the relevance of monocytes or macrophages and CD47 in vivo, Alexa Fluor®594 anti-CD68 antibody and HE staining was performed to detect macrophages in the gastric tumour xenograft model." (PMID 35694254, 2022).
T cell lymphoma (7 papers, 2019 to 2024). "Consistent with the ICI analysis on the surface of cancer cells, AccuTOX® combined with anti-CD47 (yellow line) was substantially superior than AccuTOX® alone (green line) at inhibiting EL4 T-cell lymphoma growth." (PMID 38831284, 2024). "Both PD1/PD-L1 and CD47 blockades have demonstrated limited activity in most subtypes of NHL save NK/T-cell lymphoma." (PMID 37012357, 2023). "For example, CD47–TSP-1 interaction promoted tumor progression in a T cell lymphoma model by supporting proliferation, survival, and migration via activation of ERK, AKT and survivin signaling." (PMID 37958404, 2023). "Immortalized T cell lymphoma cells (Jurkat) were used as target tumor cells because they express high levels of CD47." (PMID 31189095, 2019). "Anti-CD47 monoclonal antibodies induced the selective phagocytosis of T-cell lymphoma by macrophages in vitro and in murine patient-derived xenograft or immunocompetent T-cell lymphoma models, although the PTCL-NOS cell line was found to be resistant." (PMID 35743749, 2022). "CD47 was found to be heterogeneously expressed in T-cell-lymphoma cell lines." (PMID 35743749, 2022). "Herein, we report on the complimentary interactions of a rationally designed and dual targeted BsAb (CD47 x PD1), HX-009, which appears to exhibit superior activity over the monotherapies in various preclinical models of B- and T-cell lymphomas." (PMID 37012357, 2023). "While they are rarely expressed on T cell lymphomas, LAG3 is expressed on CD4+ and CD8+ tumor-infiltrating lymphocytes and could be a druggable target alone or in combination with CD47." (PMID 36429020, 2022).
autoimmune hemolytic anemia (6 papers, 2013 to 2024). Autoimmune hemolytic anemia (AIHA) is an autoimmune disorder in which various types of auto-antibodies are directed against red blood cells causing their survival to be shortened and resulting in hemolytic anemia. "CD47-SIRPα has been proposed as a regulator in the development of T cell-mediated autoimmune pathogenesis, including multiple sclerosis (MS), autoimmune hemolytic anemia (AIHA) and autoimmune diabetes." (PMID 38125492, 2023). "Owing to highly expressed CD47 on normal red blood cells, disruption of CD47/SIRPα axis may result in lethal autoimmune hemolytic anemia." (PMID 39429877, 2024). "In mice, it has been shown that CD47–SIRPα interactions have a profound effect on disease severity of autoimmune hemolytic anemia (AIHA)." (PMID 28210260, 2017).
follicular lymphoma (6 papers, 2020 to 2023). Follicular lymphoma is a form of non-Hodgkin lymphoma characterized by a proliferation of B cells whose nodular structure of follicular architecture is preserved. "For instance, anti‐CD47 associated with Rituximab showed promising activity in heavily pre‐treated NHL (DLBCL and Follicular Lymphoma), obtaining clinical response even in those patients with diseases that were refractory to Rituximab." (PMID 37654003, 2023).
fungal infections (6 papers, 2015 to 2022). "Expression of CD47 on neutrophils is also implicated in inducing their transmigration in both bacterial and fungal infections." (PMID 33123143, 2020). "Expression of CD47 and CD11b on neutrophils is pivotal for neutrophil transmigration and defense against both bacterial and fungal infections." (PMID 33123143, 2020). "Based on its known immune functions, CD47 could play both protective and sensitizing roles in fungal infections." (PMID 26010544, 2015). "Biopsy results demonstrated CD4 positivity, consistent with Mycosis Fungoides with coexpression of CD5, CD47, and CD7." (PMID 26380134, 2015).
pancreatic adenocarcinoma (6 papers, 2020 to 2025). "We checked the mRNA expressions of CD47 and ERM family members in 50 human pancreatic adenocarcinoma cell lines registered in the public databases of the Cancer Cell Line Encyclopedia (CCLE) and Cancer Dependency Map (DepMap) portal." (PMID 37189735, 2023). "In summary, our analysis confirmed the role of 2 genes (CD47 and SCL44A1) in 2 cancer types (uterine corpus endometrial carcinoma and pancreatic adenocarcinoma, respectively) and highlighted 5 novel marker candidates in 6 cancer types." (PMID 34439361, 2021). "Indole-3-carbinol affects the expression of 5 different genes (CD47, CENPB, ERGIC1, PPRC1, SLC44A1) that, in turn, affect the survival in patients with uterine corpus endometrial carcinoma (CD47), brain lower-grade glioma (CENPB, ERGIC1) and pancreatic adenocarcinoma (PPRC1, SLC44A1), respectively." (PMID 34439361, 2021).
acute kidney injury (5 papers, 2021 to 2025). Sudden and sustained deterioration of the kidney function characterized by decreased glomerular filtration rate, increased serum creatinine or oliguria. "Treatment with anti-CD47 mAb improved renal failure (serum creatinine: anti-CD47 mAb, 0.96 ± 0.30 mg/dL, versus CT-Ab, 0.61 ± 0.32 mg/dL; P <0.05) and attenuated kidney injury in histopathological examination (glomerular score: anti-CD47 mAb, 2.0 ± 0.63, versus CT-Ab, 2.8 ± 0.41; P <0.05)." (PMID 37368493, 2023). "Previous studies have demonstrated that THBS1 binds to CD47 to promote acute kidney injury (AKI), and blocking THBS1 signalling by CD47 alleviates renal interstitial fibrosis." (PMID 40977522, 2025).
chronic myeloid leukemia (5 papers, 2019 to 2024). "Conversely, the selective HDAC6 inhibitor Rocilinostat, which did not induce SLFN11 in K562 chronic myelogenous leukemia or HT1080 fibrosarcoma cells, was 1.51-fold less potent for CD47− vs. WT cells in the CellTiter Glo assay and was less potent for inhibiting proliferation of CD47− cells." (PMID 31632920, 2019).
Cognitive impairment (5 papers, 2022 to 2026). Abnormal cognition is characterized by deficits in thinking, reasoning, or remembering. "In a mouse model of postoperative cognitive dysfunction, the downregulation of CD47 and SIRPα expression in the hippocampus was associated with increased microglial synaptic pruning, leading to synaptic loss and the exacerbation of cognitive impairment." (PMID 40313098, 2026). "CD47 expression has been linked to synaptic refinement and various behavioral and cognitive disorders." (PMID 40140948, 2025). "Together, these results suggest that both C1q and CD47 are dysregulated with age and likely contribute to both the increase in microglia reactivity and vulnerability of myelin to phagocytosis that is associated with cognitive impairment." (PMID 39399501, 2024). "In addition, the efficiency of AAV transduction in microglia is limited, which may affect the result, although we found reduced expression of CD47 and SIRPα and increased synaptic engulfment, synapse loss, and cognitive impairment in PND model." (PMID 35360151, 2022). "We believe the changes in C1q and CD47 reported here are detrimental to white matter during aging as they are correlated with worsening cognitive impairment." (PMID 39399501, 2024). "Results showed a significant decrease in CD47 in the old age group (38.7% decrease, p= 0.0019) and with cognitive impairment (34.3% decrease, p= 0.027)." (PMID 39399501, 2024). "Importantly, the knockout of SIRPα impaired CD47 recognition, thus resulting in exacerbated synaptic pruning and cognitive deficits." (PMID 40313098, 2026). "Finally, these changes in C1q, CD47, and microglia phenotypes correlate with more severe cognitive impairment." (PMID 39399501, 2024). "Since these signals have not been studied in aging white matter tracts in relation to myelin damage and related cognitive impairment, the present study aimed to assess changes in the balance of C1q and CD47 in the white matter of the aging cingulum bundle in cognitively assessed nonhuman primates." (PMID 39399501, 2024). "SIRPα overexpression led to decreased PSD95 expression and dendritic spine density, but without worse cognitive impairment, which may also due to complex body regulation and downstream mechanisms of CD47–SIRPα signal." (PMID 35360151, 2022).
cutaneous T-cell lymphomas (5 papers, 2020 to 2025). "In addition to overexpression of CD47 by cancer cells as a survival mechanism, TSP-1 ligation of CD47 is shown to increase proliferation and survival of cutaneous T-cell lymphomas (CTCL) and hence blockade of CD47/TSP-1 interaction results in CTCL regression." (PMID 32882841, 2020). "In cutaneous T cell lymphoma (CTCL), TME with higher CD47 checkpoint inhibition correlated with advanced disease state." (PMID 34584838, 2021). "Immune checkpoint inhibition to activate exhausted nonmalignant T cells (PD-1/PD-L1 axis) or modulation of the CD47-SIRPalpha axis to promote macrophage antitumor immune responses are other promising novel therapies of cutaneous T-cell lymphomas." (PMID 36765704, 2023). "Cutaneous T-cell lymphoma (CTCL) is not an exception; moreover, significant overexpression of CD47 in Sézary syndrome and mycosis fungoides makes CTLC an ideal candidate for anti-CD47 therapy." (PMID 36429020, 2022).
depression (5 papers, 2014 to 2025). "We also pointed to a genetic association with psychiatric phenomena like psychosis, depression, ADHD, and SUDs, observed through several mutual genes, such as CADM2, TCF4, LINC02758, and CD47, and via genetic correlations." (PMID 40736093, 2025). "A number of individual top biomarkers are known to be modulated by medications in current clinical use for treating depression, such as by lithium (NRG1, PRPS1, CD47), antidepressants (SLC6A4, DOCK10, NRG1, CD47) and the nutraceutical omega-3 fatty acids (GLO1, SLC6A4, CD47, GLS, HNRNPDL)." (PMID 33828235, 2021).
heart failure (5 papers, 2016 to 2026). Inability of the heart to pump blood at an adequate rate to meet tissue metabolic requirements. "We have thus confirmed that CD47 deficiency exerts cardioprotective effects against ISO-induced cardiac remodeling by inhibiting heart failure, cardiac fibrosis, and cardiac hypertrophy." (PMID 31827695, 2019). "Recently, studies showed that CD47 inhibition protects against myocardial I/R injury and heart failure." (PMID 34349643, 2021). "Accordingly, blockade of either CD47, HDAC3 or CaMKII has beneficial cardiac effects by reducing hypertrophy and softening heart failure thereby underlining a value of the TSP1/CD47 pathway in the pathogenesis of heart failure." (PMID 28714932, 2017). "The TSP1/CD47 signaling seems to play a central role in promoting left ventricular hypertrophy and heart failure." (PMID 28714932, 2017). "A key focus is how efferocytic dysfunction (e.g., MerTK cleavage, CD47 upregulation, Lgmn blockade) triggers a self-perpetuating vicious cycle of failed clearance, sustained inflammation, and repair collapse, leading to adverse remodeling and heart failure." (PMID 41878419, 2026). "In heart hypertrophy, atherosclerosis, heart failure, and MI, the down-regulation of the TSP/CD47 axis to enhance angiogenesis and restore NO-dependent signaling would be beneficial." (PMID 28714932, 2017).
Hyperglycemia (5 papers, 2009 to 2025). An increased concentration of glucose in the blood. "The extracellular domain of CD47 was previously shown to be shed from the surface of vascular smooth muscle cells via proteolytic cleavage, which was suppressed under conditions of hyperglycemia." (PMID 40943300, 2025). "While the aorta homogenates contain a mixture of cells including, SMC, the data supports our in vitro findings that hyperglycemia is associated with an increase in TSP-1 and CD47/IAP." (PMID 20689700, 2010). "Using RNAi to reduce TSP-1 protein levels and a peptide homologous to the CD47/IAP binding site of TSP-1 we were able to demonstrate that the enhancing effect of hyperglycemia on IGF-I signaling was mediated by TSP-1 binding to CD47/IAP." (PMID 20689700, 2010). "Using genetic and pharmacological approaches to modulate CD47 signalling capability, we reveal that CD47 inhibition improves anti-apoptotic, senescence, autophagic and self-renewal responses to hypoxia, hyperglycaemia or ER stress in MIN6 cells, as well as primary mouse and human islets." (PMID 40133488, 2025). "Hyperglycemia protected CD47 from cleavage, resulting in increased CD47 levels." (PMID 34698067, 2021). "TSP1 is upregulated in endothelial cells in response to hyperglycaemia and we replicated this finding in human islets, demonstrating increased TSP1 and CD47 expression by western blot and immunofluorescent staining." (PMID 40133488, 2025).